TBX2 (T-box transcription factor 2)
Diseases named in the same sentence as TBX2 in open-access papers (continued):
Sharing a sentence is not in itself a finding about the gene and the disease.
cancer (continued). "Epithelial–mesenchymal transition (EMT), invasion and migration are key processes that facilitate cancer metastasis and progression, and TBX2 has been found to promote these processes in several cancers." (PMID 39912718, 2025). "More in-depth studies are required to confirm if these mechanisms are relevant to all TBX2-dependent cancers or if there are other novel molecular mechanisms involved." (PMID 39912718, 2025). "Niclosamide, piroctone olamine, and pyrvinium pamoate are promising, cost‐effective therapeutic agents for the treatment of TBX2/TBX3‐dependent cancers." (PMID 39403898, 2024). "The pro-cancer mechanism of TBX2 primarily occurs through the induction of cells to bypass senescence." (PMID 38965548, 2024). "It suggests that combining targeted therapy against TBX2 with chemotherapeutic agents such as cisplatin can enhance the effectiveness of current anti-cancer treatments." (PMID 38965548, 2024). "Niclosamide, piroctone olamine, and pyrvinium pamoate have been shown to exhibit anti‐cancer activity through their ability to inhibit signalling pathways such as the WNT/B‐catenin that can transcriptionally activate TBX2/TBX3." (PMID 39403898, 2024). "We have found significant genes (SASH1, TBX2, HBEGF, etc.)linked to NSCLC cancer that can serve as potential drug targets." (PMID 37324026, 2023). "In some previous studies, it was suggested that T-box factors, especially Tbx2, as transcription factors, play important roles in controlling cell cycle progression, embryonic development, and cancer genesis." (PMID 35180880, 2022). "Our results provide key insights into how PI3K signaling modulates TBX2 function in cancer to drive proliferation." (PMID 34819350, 2021). "The role of TBX2 has been widely studied in development of the heart and the mammary gland, and in cancers such as breast cancer, melanoma, lung cancer, liver and prostate cancer." (PMID 34064060, 2021). "Further activated transcription regulators, such as β-catenin, Foxm1, Irf1, Myc, Mitf, Tbx2 with a somewhat lower z-score did also point to cell cycle regulation, DNA damage and cancer development." (PMID 32419051, 2020). "More importantly, the potential for using TBX2 as a target in cancer therapy is now being explored 13,17." (PMID 32231721, 2020). "we found TBX2, along with 10 other genes, to be reported with relevance to bone metastasis in other cancer types." (PMID 31897234, 2020). "The TBX2 transcription factor plays critical roles during embryonic development and it is overexpressed in several cancers, where it contributes to key oncogenic processes including the promotion of proliferation and bypass of senescence." (PMID 32195221, 2020). "Increasing evidence has established that TBX2 plays a role in the progression of a number of cancers 11-14,16." (PMID 32231721, 2020). "Any drug that therefore impacts TBX2 expression or activity is likely to have a major impact on cancer progression and recurrence." (PMID 32195221, 2020). "This analysis suggested the hypermethylation of TWIST1, CDKN2A (ARF2), PIK3R5 and TBX2 are present in cancers of the breast, colon, lung and prostate." (PMID 33143142, 2020). "We also examined the tumor suppressor and pro-apoptotic gene, phosphatase and tension homolog detected on chromosome 10 (PTEN), which is known to be activated by EGR1 and repressed by TBX2 in many cancer types." (PMID 29719592, 2018). "TBX2 functions as a repressor of transcription, which inhibits promoter activity of a number of cancer-suppressing genes." (PMID 28881763, 2017). "Collectively, our results uncover an unanticipated link between TBX2 deregulation in cancer and the acquisition of EMT and invasive features of epithelial tumor cells." (PMID 22844464, 2012). "To elucidate the potential role of TBX2 in malignant tumor progression, we employed RNA interference strategies to inhibit TBX2 in the metastatic breast carcinoma cell lines MDA-MB-435 and MDA-MB-157." (PMID 22844464, 2012).
cancer (continued). "Tbx2 and Tbx3, both of which are transcriptional repressors, have been found to be amplified or over-expressed in various cancer types." (PMID 23082988, 2012). "Depleting TBX2 in cancers addicted to it inhibits key hallmarks of cancer." (PMID 39912718, 2025). "Furthermore, TBX2 and TBX3 play distinct but causative oncogenic roles in cancers where they are both expressed, and they repress one another to achieve these functions." (PMID 40717225, 2025). "However, to the best of our knowledge, there are only two reports that have identified anti-cancer agents that function specifically through their ability to inhibit TBX2." (PMID 39912718, 2025). "A better understanding of how TBX2 confers resistance to a range of cancer treatments could also inform the feasibility of combining TBX2 inhibitors with other therapies such as DNA-damaging agents." (PMID 39912718, 2025). "While TBX2 has no known function in adult tissue, its postnatal deregulation has been associated with the neurodegenerative disorder, Alzheimer’s disease, and cancer." (PMID 39912718, 2025). "Understanding the complex molecular networks that TBX2 is involved in to exert its oncogenic functions is important because it may reveal potential therapeutic strategies for targeting TBX2 in TBX2-dependent cancers." (PMID 39912718, 2025). "While limited information is available on how TBX2 is regulated in cancers, there is evidence that the levels and oncogenic functions of TBX2 are induced by developmental signalling pathways that are hijacked by cancer cells such as the Wnt/β-catenin and PI3K/AKT pathways." (PMID 39912718, 2025). "Understanding the mechanism(s) by which these drugs exert their anti‐cancer activity may provide insight into how they are downregulating TBX2/3." (PMID 39403898, 2024). "This study therefore explored targeting TBX2/TBX3 with commercially available non‐cancer drugs." (PMID 39403898, 2024). "TBX2 forms complexes with critical molecules synergistically exerting cancer-promoting effects." (PMID 38965548, 2024). "Although TBX2 has been extensively studied in cancer cells, its biological functions in bovine cumulus cells remain unclear." (PMID 36446749, 2023). "Although TBX2 has been widely studied in cancer cell growth and development, its biological functions in bovine cumulus cells remain unclear." (PMID 36446749, 2023). "These correlations suggest that targeting TBX2-CoREST may represent a novel therapeutic approach for targeting the poorest outcome cancers within the TNBC subtype." (PMID 35687133, 2022). "Overall these comparisons provide strong evidence for a tissue-specific model of TBX2 engagement with chromatin, mediated indirectly through interaction with core TFs which may vary significantly between cancer subtypes." (PMID 35687133, 2022). "TBX2, a member of the T-box transcription factor family, is overexpressed in several cancers and may have a potential role in tumorigenesis as an immortalizing agent." (PMID 34738870, 2021). "Third, the underlying mechanism of cancer progression and drug resistance induced by TBX2 expression in GC has not been elucidated." (PMID 32231721, 2020). "Taken together, these results suggest that TBX2 may be an attractive new target for advanced stage cancer therapy." (PMID 32231721, 2020). "TBX2 is a member of the T-box family of transcription factors with an important role during embryogenesis and morphogenesis and is overexpressed in several cancer entities including melanoma, breast, and pancreatic cancer." (PMID 30451831, 2018). "Up-regulation of TBX2 has been reported in a wide range types of cancer." (PMID 28881763, 2017). "Knockdown of TBX2 in the NPC cells inhibits cancer cell proliferation and invasion." (PMID 28881763, 2017). "Despite the importance of TBX2 in tumorigenesis of various cancers, the expression and biological functions of TBX2 in NPC are still largely unknown." (PMID 28881763, 2017).
cancer (continued). "This salient role in metastasis makes TBX2/3 an interesting target in cancer therapy." (PMID 25344916, 2014). "In some cancers, the level or activity of TBX2/3 appear to control cellular motility." (PMID 25344916, 2014). "Increasing evidence suggests that Tbx2 and Tbx3 may regulate proliferation in cancer and in development and our data is consistent with a role for these T-box genes downstream of BMP4 in regulating proliferation of the optic cup." (PMID 17173667, 2006). "Furthermore, there is strong in vitro and in vivo biological evidence that TBX2 may be a novel target for anti-cancer drugs that can be administered on their own or in combination with other chemotherapies." (PMID 32195221, 2020). "In cancer, TGF-β1–induced upregulation of Tbx3 leads to repression of Tbx2, thereby promoting cell migration and invasion." (PMID 41278973, 2025). "This is important because TBX2 and TBX3 can transcriptionally repress one another in certain contexts, and they have been shown to have distinct oncogenic roles in cancers where they are both expressed." (PMID 39912718, 2025). "Upstream regulators of TBX2 include PI3K/AKT and Wnt/β-catenin, and inhibitors to these pathways have been identified that demonstrate efficacy in several cancers." (PMID 39912718, 2025). "This is important because it will shed light on versatile ways of targeting TBX2 and TBX3 in cancer therapies." (PMID 39403898, 2024). "A survey of literature suggests the hypermethylation of the associated proteins, including PIK3R5, TBX2 and TWIST1 individually, have multiple biological functions in various cancers, and could serve as potential methylation targets to screen for onset of different cancers." (PMID 33143142, 2020). "Taken together, the data show that TCEA3 is silenced by DNA methylation and suggests a possible mechanism for how TBX2 represses TCEA3 expression in RMS and additional cancer types." (PMID 31988307, 2020). "In contrast, over-expression of the Tbx2-subfamily genes TBX2 and TBX3 is found in a number of human cancers." (PMID 23595631, 2013). "Taken together, TBX2 and TBX3 act as suppressors of senescence factors such as CDKNs, and hence, suppress senescence especially in cancer cells; thus, TBX2 and TBX3 are thought to be critical anti-senescence factors." (PMID 22829758, 2012). "Not surprisingly, TBX2 has been identified and biologically validated as a promising prognostic marker and drug target in cancers where it is overexpressed." (PMID 39912718, 2025). "Importantly, when TBX2 and TBX3 are depleted in cancers where they are overexpressed, the malignant phenotype is inhibited, and they have therefore been regarded as druggable targets." (PMID 39403898, 2024). "They activate cancer cell signaling pathways and transcription factors, including IGF1/α6β4 complex, FGFR2, TIMP, DNA replication and mTOR signaling, Smad7, KLF4, and TBX2, and downstream proto-oncogenes such as MYC, MET, and CDK1, which facilitate cancer progression." (PMID 37046676, 2023). "Furthermore, we uncover that TBX2/CoREST targeting of NDRG1 is achieved by recruitment of TBX2 to the NDRG1 promoter by Sp1, the abolishment of which resulted in NDRG1 upregulation and diminished cancer cell proliferation." (PMID 35687133, 2022). "The transcription factors TBX2 and TBX3 are overexpressed in various human cancers." (PMID 25344916, 2014). "TBX2 and its close relative, TBX3, negatively regulate cell cycle control genes and CDKNs, specifically CDKN2A, CDKN2B, and CDKN1A and are often upregulated in several cancers." (PMID 22829758, 2012). "In this regard, it is worth noting that there are inhibitors to known TBX2 co-factors (e.g. HDAC1/2 and Sp1) and upstream regulators (e.g. PI3K/AKT and Wnt/β-catenin) that are already FDA-approved or currently undergoing clinical evaluation for their therapeutic potential in cancer treatment." (PMID 39912718, 2025).
cancer (continued). "Furthermore, there is strong in vitro and in vivo biological evidence that TBX2 and TBX3 are novel targets for the development of anti‐cancer drugs that can be administered on their own or in combination with current chemotherapeutic DNA‐damaging drugs such as cisplatin." (PMID 39403898, 2024). "Taken together, it would thus appear that there is an intricate link between the Wnt/β‐catenin pathway and TBX2/3 and that any drug that inhibits this pathway may negatively impact TBX2/3‐driven cancers." (PMID 39403898, 2024). "The endothelial Duffy antigen receptor for chemokines (DARC) may induce dormancy in cancer cells by binding to the metastasis suppressor cluster of differentiation 82 (KAI1), inhibiting proliferation through p21Waf1 and downregulating T-Box transcription factor 2 (TBX2)." (PMID 37296983, 2023). "It is likely that TBX2 and/or TBX3 account for the function of HDACs in repression of cyclin-dependent kinase inhibitor gene expression in at least some cancer types, and that TBX2 or of its specific interaction with HDACs represent valuable highly specific targets for anti-cancer therapy." (PMID 33731112, 2021). "Moreover, IPA analysis shows that OU and Digo could reduce the activity of many transcription factors in which overexpression is required for sustained proliferation and cancer progression (e.g., NRF2, SOX11, TBX2)." (PMID 33352737, 2020). "It would therefore be interesting to determine whether the highly homologous TBX2 and TBX3 have redundant functions in regulating the p21 promoter at this site in cancers where they are both expressed or whether the availability of cofactors may determine which one of the two regulates p21." (PMID 27110270, 2016). "While no studies have previously been published in other cancer cell lines for transient overexpression of TBX4 and 5, numerous studies have shown that transient overexpression of TBX2 or TBX3 does specifically affect senescence by targeting the tumor suppressor gene CDKN1A and B, and CDKN2A." (PMID 30425966, 2018). "However, there is still a paucity of information regarding its anti‐cancer activities and mechanisms of action in PDAC and whether it inhibits TBX2/3 proteins in PDAC is not known." (PMID 40717225, 2025).
infection (2 papers, 2015 to 2023). The state of being infected such as from the introduction of a foreign agent such as serum, vaccine, antigenic substance or organism. "Upstream modifiers associated with the adaptive immune response including Tbx2, Foxo1, and the TCR rise in significance after day 5 post-infection and stay elevated to the end of the experiment." (PMID 26413862, 2015). "On days 5 and 15 PI, TBX2 mRNA expressions and the levels of IFN-γ and TNF-α in serum were significantly increased after the infection compared to the control group." (PMID 37593762, 2023). "We found that levels of TBX2, GATA3, RORC, SPI1, and BCL6 in the livers of infected rabbits were elevated on days 5 and 15 post-infection (PI)." (PMID 37593762, 2023). "Mechanistically, TBX2-dependent innate IFN-γ is essential in T. gondii infection T-bet to produce IFN-γ, which is essential for host resistance to intracellular infection by maintaining IRF8 inflammatory dendritic cells at the infection site." (PMID 37593762, 2023).
skeletal dysplasia (1 paper, 2022). Any Mendelian diseases that affects growth and development of the skeleton. "Whole-exome sequencing excluded known skeletal dysplasias and identified a novel heterozygous missense mutation c.899C>T (p.Thr300Met) in TBX2, confirmed by Sanger sequencing." (PMID 35311234, 2022). "Future reports on other TBX2 variants in skeletal disorders will be helpful in further delineating the TBX2-associated skeletal dysplasia." (PMID 35311234, 2022). "Our findings expand the current spectrum of skeletal dysplasias, support the association of TBX2 mutations with skeletal dysplasia and suggest a role for TBX2 in development of the spinal and craniofacial structures and the pituitary gland." (PMID 35311234, 2022). "Clinical characteristics in the three Finnish patients with a novel skeletal dysplasia, compared with previously reported findings in TBX2 mutation-positive individuals." (PMID 35311234, 2022). "Our results resonate with known roles of TBX2 in skeletal and central nervous system development and also underpin the complexity and still partly unknown genetic landscape of skeletal dysplasias." (PMID 35311234, 2022).
TBX2 also shares sentences with these, for which no sentence is quoted: colon cancer (2 papers); colorectal cancer (2); glioma (2); liver cancer (2); non-small cell lung carcinoma (2); Arthritis (1); breast (1); developmental delay (1); Esophageal atresia (1); heart defects (1); heart failure (1); hepatocellular carcinoma (1); Hodgkins lymphoma (1); hypertension (1); leukemia (1); liposarcoma (1); lymphoma (1); metastatic cancer (1); metastatic tumor (1); microcephaly (1); Mohr Syndrome (1); nephritis (1); osteochondrodysplasia (1); renal dysplasia (1); rheumatoid arthritis (1); schizophrenia (1); small cell lung carcinoma (1); triple-negative breast carcinoma (1); Wolff-Parkinson-White syndrome (1).